U3 (Small nucleolar RNA U3 )
Synonyms: LOC124904671
Gene: Small nucleolar RNA gene on chromosome 1 (163,923,670 to 163,923,873, forward strand). Ensembl gene ENSG00000212538.
Gene Ontology:
Biological process: RNA processing
Cellular component: nucleolus
Homologues: Orthologues: chimpanzee U3 (99% identical). Paralogues in human: SNORD3P1 (78% identical), U3 (77% identical), SNORD3E (76% identical), U3 (76% identical), SNORD3D (75% identical), U3 (75% identical), SNORD3H (75% identical), SNORD3G (74% identical), U3 (74% identical), U3 (73% identical), U3 (72% identical), U3 (71% identical), and 12 more.